CEP15 (centrosomal protein 15)
Description:
May play a role in ciliary assembly.
Synonyms: C3orf14; HT021
Tractability: Antibody: the Human Protein Atlas places it where antibodies can reach.
Gene: Protein-coding gene on chromosome 3 (62,319,015 to 62,336,213, forward strand). Ensembl gene ENSG00000114405.
Subcellular location: Cell projection, cilium
Subcellular location (Human Protein Atlas): Plasma membrane; Cytosol
Gene Ontology:
Cellular component: cilium
Genetic constraint (gnomAD): Loss-of-function variants: 12 observed, 13.01 expected, observed/expected ratio (o/e) 0.92, 90% interval 0.59 to 1.49. The upper end of that interval is the gene's LOEUF score, 1.49, which puts it in group 6 of 6, group 1 being the genes least tolerant of losing a copy. Missense variants: 99 observed, 106.19 expected, observed/expected ratio (o/e) 0.93, 90% interval 0.79 to 1.1. Synonymous variants: 30 observed, 34.63 expected, observed/expected ratio (o/e) 0.87, 90% interval 0.65 to 1.17.
Homologues: Orthologues: chimpanzee CEP15 (99% identical), macaque CEP15 (98% identical), pig CEP15 (86% identical), dog C20H3orf14 (83% identical), rabbit CEP15 (83% identical), mouse Cep15 (68% identical), rat Cep15 (63% identical), guinea pig CEP15 (52% identical), zebrafish CEP15 (41% identical), tropical clawed frog CEP15 (37% identical).
Diseases named in the same sentence as CEP15 in open-access papers:
CEP15 is named in the same sentence as 7 diseases in open-access papers, as found by Europe PMC text mining. Sharing a sentence is not in itself a finding about the gene and the disease. The quoted sentences say what the papers report.
cancer (2 papers, 2010 to 2020). A tumor composed of atypical neoplastic, often pleomorphic cells that invade other tissues. "This evaluation generated a set of 5 probes that detected copy gains in ≤ 10% of CIN1, and ≥ 70% of CIN2/3 and Cancer lesions: 8q24, 20q13, Xp22, 1p31, and CEP15 probes." (PMID 20712890, 2010).
bacterial infection (1 paper, 2025). "Only the expression of CEP15 is slightly repressed upon bacterial infection, raising the question whether CEP15 transcript abundance is actively suppressed by Pto DC3000." (PMID 40982539, 2025). "Collectively, this data, together with our group II CEP overexpression analysis, indicates that class II CEPs are important components of cell surface receptor-mediated immunity against bacterial infection in Arabidopsis with a more prominent role for CEP14 and CEP15." (PMID 40982539, 2025).
infection (1 paper, 2025). The state of being infected such as from the introduction of a foreign agent such as serum, vaccine, antigenic substance or organism. "Consistent with publicly available RNA-seq data, CEP15 expression was suppressed during infection with Pto DC3000, whereas MAMP treatments did not result in marked transcript changes." (PMID 40982539, 2025).
CEP15 also shares sentences with these, for which no sentence is quoted: glioblastoma (2 papers); colorectal cancer (1); liver cancer (1); prostate carcinoma (1).